VIM (vimentin)
Diseases named in the same sentence as VIM in open-access papers (continued):
Sharing a sentence is not in itself a finding about the gene and the disease.
tumor (continued). "Although Vimentin is critical in maintaining cell structures and may promote tumor progression, it is seemingly not an essential factor for survival under normal physical condition." (PMID 31428643, 2019). "Moreover, immunohistochemical analysis suggested that the slower tumor growth rate and the reduced metastasis by miR-25 inhibition were, at least in part, due to the upregulation of LATS2 and E-cadherin expression and the downregulation of Vimentin and MMP9." (PMID 31316723, 2019). "We found that all tumor cells exhibited membranous E-cadherin staining, and Vimentin could only be found in stromal cells, but not HCC cells, of either Sgk3 wild-type or KO mice." (PMID 30975125, 2019). "The detected smooth muscle actin (SMA)-, vimentin-, or calponin-positive epithelial tumor areas could contain retained non-neoplastic ME cells or tumor cells with the expression of these markers." (PMID 31569405, 2019). "Similarly, cell lines derived from the other tumor resections did not express detectable levels of E-cadherin or Pan-cytokeratin but were also highly vimentin positive." (PMID 30862796, 2019). "Interestingly, TAZ knockdown resulted in a marked increase in tumor suppressor IGFBP3 expression and complete inhibition of EMT‐associated VIM expression, but YAP did not influence the expression of these genes." (PMID 31633304, 2019). "However, whether the epigenetic regulation of E-cadherin and Vimentin would affect the regulatory pathway of JAG2 and tumor metastasis and the universality of JAG2 related pathways are still worthy of further exploration." (PMID 31198409, 2019). "Furthermore, the endogenous expression of CD44, N-casherin, Vimentin, Snail, and VEGF in tumor tissue from the U87 xenograft mice was suppressed by galangin treatment, indicating that galangin inhibited EMT and angiogenesis in the orthotopic xenograft mouse model." (PMID 31528214, 2019). "In addition, there was a negative correlation of E‐cadherin expression with tumor stage (correlation coefficient −0.364, P = 0.001), while there was a positive correlation between Vimentin staining and tumor stage (correlation coefficient 0.398, P = 0.001)." (PMID 30714677, 2019). "In addition, a minor population of tumor cells exhibited co-staining for both CEACAM5 and vimentin." (PMID 29736411, 2018). "Stratification of patients within the TCGA cohort according to tumor size disclosed higher expression of EpCAM expression in bigger tumors (T-classification 3–4 versus 1–2) (Mann-Whitney p-value = 0.013), whereas Sox2 and vimentin expression did not correlate with tumor size." (PMID 30275505, 2018). "Compared with control injections of HCC-Mock’ cells and hepatic stellate cells, the tumours produced by injecting HCC-shTGM2 cells and hepatic stellate cells were marked by significantly lighter weight, showing increased E-cadherin expression and reduced vimentin expression." (PMID 30393774, 2018). "The undifferentiated tumour cell population had no high-molecular-weight cytokeratin (34βE12), showed diffuse positive cytoplasmic expression of pan-cytokeratin, negative E-cadherin expression and strong vimentin expression." (PMID 29144834, 2018). "As our in vitro studies revealed changes in the expression of mesenchymal proteins, Snail and Vimentin, and in the activity of MMP-2 and MMP-9 on cancer cells treated with Kp-10, we also investigated whether the Kisspeptin treatment blocks tumor metastatic behavior in vivo." (PMID 29721201, 2018). "In cultured RCC cells, knockdown of G3BP1 results in inhibition of tumor cell proliferation, migration, and invasion, consistently with the alteration of epithelial–mesenchymal transition (EMT) and cell proliferative markers, including Cadherins, Vimentin, Snail, Slug, c-Myc, and cyclin D1." (PMID 29717134, 2018).
tumor (continued). "SOX2, vimentin and E-cadherin expression was assessed by immunohistochemical staining on serial sections from formalin fixed and paraffin embedded tissue samples of a patient cohort (n = 45) with primary ACC and correlated with patient and tumor characteristics as well as survival." (PMID 29596469, 2018). "In addition to activating the JAK/STAT3 pathway via phosphorylation of STAT3, the IL-6/IL-6R interaction leads to low E-cadherin expression and high vimentin expression as well as upregulated expression of Snail, ZEB1, ZEB2, Twist and other transcription factors that promote tumor metastasis." (PMID 30157906, 2018). "In order to exclude that vimentin+ cells in tumor areas represented infiltrating non-tumor cells, selected tumor specimens were stained with vimentin- and either CD31- (endothelial cells), CD68- (monocytes/macrophages), or CD90-specific antibodies (fibroblasts), respectively." (PMID 30275505, 2018). "Histopathological examination revealed a tumor composed of malignant epithelioid cells, which on immunohistochemical examination stained positive for cytokeratin (CK) AE1/AE3 (diffuse), CK7 (focally), CD10, vimentin, and epithelial membrane antigen (EMA; scattered tumor cells)." (PMID 28343447, 2017). "The anti-tumor effect of EA might be related to cell cycle arrest, down-regulating the expression of COX-2 and NF-κB, reversing epithelial to mesenchymal transition by up-regulating E-cadherin and down-regulating Vimentin." (PMID 28135203, 2017). "As seen in Yamato-SS xenograft models, not only spindle cells but also epithelial tumour cells were observed in SYO-1 xenograft tumours after TAS-115 administration, which was confirmed by immunohistochemical staining of anti-vimentin and anti-cytokeratin (AE1/AE3) antibodies." (PMID 28511645, 2017). "In contrast, neither the primary tumor sample nor LT22s showed expression of Vimentin." (PMID 28855609, 2017). "The origin of LT22a cells was rather unclear, because in the primary tumor a Vimentin positive cell subpopulation could not be detected." (PMID 28855609, 2017). "However, E-cadherin expression (p = 0.621) and Vimentin expression (p = 0.132) were not significantly reduced and elevated, respectively, in tumor tissues compared with the normal tissues." (PMID 28570699, 2017). "In addition, CAPN2-OV could enhance N-cadherin, Vimentin and MMP9 protein level in CAKI-2 cells, which highlights the promoting role of CAPN2 in tumor metastasis in RCC." (PMID 29228653, 2017). "Vimentin was negative in tumor cells, but stained the mesenchymal cells of the chicken egg." (PMID 28855609, 2017). "However, only the mRNA level of Vimentin in the urine was found with difference (P = 0.03), not in the tumor (P = 0.16)." (PMID 28166762, 2017). "Additionally, there is no statistical difference between vimentin expression and primary tumor size." (PMID 28421110, 2017). "Also the tumor polyhedral cells had an intense nuclear reactivity for p63, and with the cytoplasm slightly positive for vimentin, but negative for α-smooth muscle actin." (PMID 27871286, 2016). "The observation in relation with the negative expression of vimentin in the ductal area of the invasive tumor shows that tumor cells in question are not fully converted to mesechymal type, rather still maintaining epithelial type, but they are aggressive and invasive." (PMID 26906973, 2016). "Moreover, tumor sections were stained for CK8, CK14 and Vimentin." (PMID 27036046, 2016). "The effects of HOXA11-AS on tumor progression may be mediated by genes involved in cell migration, invasion, and EMT-related genes; these genes include VEGF, MMP-9, MMP-2, E-cadherin, β-catenin, Vimentin, and Snail." (PMID 27792998, 2016).
tumor (continued). "However, immunohistochemical analyses of brain slices showed a reduction of U87MG cells, as identified by vimentin expression, after treatment with peptide R when compared to Plerixafor or PBS treatment, thus suggesting a reduced tumor cell density in peptide R-treated mice." (PMID 27015814, 2016). "The Shh pathway may also promote tumor cell motility and invasiveness by inducing EMT, a cellular process best characterized by decreased expression of E-cadherin and increased expression of vimentin, fibronectin and N-cadherin." (PMID 26859575, 2016). "However, evaluation of a number of genes (Zeb1, Zeb2, Twist, vimentin, etc) associated with EMT did not support the idea that SPC-IGFIR-Akt2−/− tumor cells had undergone EMT." (PMID 26654940, 2016). "Functional studies show that ectopic expression of miR-150 enhanced tumor cell metastasis in vitro and in a mouse xenograft model, and triggered EMT-like changes in NSCLC cells (including E-cadherin repression, N-cadherin and Vimentin induction, and mesenchymal morphology)." (PMID 27976702, 2016). "After KuA treatment, protein expressions of C/EBPβ, N-cadherin, vimentin, twist, slug and snail were downregulated significantly, while the expression of E-cadherin was upregulated significantly in KuA treated GBM cells and tumor tissues compared with the controls." (PMID 27824118, 2016). "In addition to these changes, in the serum-depleted proteome we observed downregulation of keratin 8, and upregulation of vimentin, the glycolytic enzymes enolase and pyruvate kinase (PKM2) and tumor progression-related inosine-5’-monophosphate dehydrogenase 2 (IMPDH2) enzyme." (PMID 28536624, 2016). "Interestingly, these samples had strong, but diffuse expression of the epithelial biomarker, cytokeratin (CK), but had low or no expression of the mesenchymal marker, vimentin in tumor cells." (PMID 27409172, 2016). "Similarly, in a case of a 9-month-old boy with mesenteric IMT, Buccoliero et al15 found that the tumor cells were positive for vimentin whereas negative for CD34 and S100 protein." (PMID 26496281, 2015). "The tumor was positive for α-smooth muscle actin and vimentin but negative for CD34 and KIT." (PMID 26697255, 2015). "Interestingly, histomorphometric analyses of total vimentin+ CAFs in tumor tissues treated by ASA with or without anti-angiogenic agents revealed a 3.4-fold reduction of CAFs upon treatment with ASA alone." (PMID 25849942, 2015). "In addition, vimentin is thought to contribute to EMT and tumor metastasis." (PMID 26516929, 2015). "Vimentin and CD68 staining in the stromal compartments of CRCs with low and high expression of TLR4 confirmed that the increased TLR4 signal was localized to PCMs and not related to tumor-associated macrophages." (PMID 24887394, 2014). "Staining for AE1/AE3, S-100, smooth muscle actin (SMA), desmin, cluster of differentiation 31 (CD31), CD34 and anaplastic lymphoma receptor tyrosine kinase (ALK) was negative, while the staining for vimentin was strongly positive (+++) with >50% positive tumor cells." (PMID 24959221, 2014). "Interestingly, we found that the expression of CRF2 ligands is inversely correlated to epithelial differentiation markers like E-cadherin (Cdh1) but correlated to mesenchymal makers like vimentin (Vim), suggesting a role of CRF2 in the cellular disorganization observed during tumor progression." (PMID 24260200, 2013). "In Prostatic stromal sarcoma (PSS) unlike the PES, immunohistochemically, the tumour cells are widely positive for vimentin, CD56, CD99 and focally positive for synaptophysin, CD10, progesterone receptor, desmin and CD34, but negative for EMA, cytokeratin, estrogen receptor, S-100 and myoglobin." (PMID 23886403, 2013).
tumor (continued). "It was able to induce epithelial-mensenchymal transition (EMT), a key event in tumor invasion and metastasis, characterized by down-regulation of epithelial markers (E-cadherin and beta-catenin) and up-regulation of mesenchymal markers (fibronectin, N-cadherin, alpha-SMA and vimentin)." (PMID 23217164, 2012). "PECs are hybrid tumor cells characterized by immunoreactivity for both melanocytic and smooth muscle markers, such as HMB45, HMSA-1, MelanA/Mart1, microphthalmia transcription factor (Mitf), actin, and, less commonly, desmin; the immunoreactivity for vimentin is usually inconspicuous." (PMID 22957287, 2012). "On microscopic examination, the tumour was found to consist of epithelial cells surrounded by a fibrous stroma and immunohistochemical examination found the tumour cells to be positive for cytokeratine and negative for vimentin." (PMID 23093972, 2012). "In addition, the residual tumor epithelial-mesenchymal transition (EMT) was enhanced (N-cadherin and Vimentin were both upregulated, but E-cadherin was downregulated), and this effect could be reversed by Tan IIA." (PMID 23137165, 2012). "Depletion of PMN-MDSC resulted in a very significant inhibition of tumor cell dissemination (85% reduction in the draining lymph node, 74% in the lung, 40% reduction in the incidence of cutaneous tumors) and EMT (68% reduction in S100A4+ cells and 70% reduction in vimentin+ cells)." (PMID 21980263, 2011). "Although the expression of TWIST1 and SNAI2 correlated with the co-activation of Vimentin and N-cadherin and hence with the initiation of a mesenchymal differentiation program, in our tumor series they failed to correlate significantly with clinical-pathological characteristics." (PMID 22201613, 2011). "Also, vimentin expressing tumours had slightly higher Ki-67 level, but without statistical significance, so this particular result is not supported by other analyses." (PMID 19695088, 2009). "In comparing the extent of stromal reaction and vimentin expression in this study, however, our data suggest that fibrous tissue itself may not be sufficient to promote tumour progression." (PMID 17325702, 2007). "In fact, in CRC, vimentin was specifically expressed in the stroma, but not in the tumour cells." (PMID 17325702, 2007). "Immunohistochemically, the tumour strongly reacted with mithochondrial antigen, keratin, alpha-1-antichymotrypsin, but was negative for smooth muscle actin, vimentin and carcinoembryonal antigen (CEA) and S-100 protein (S-100)." (PMID 16923179, 2006). "Stain for cytokeratin was negative while tumor cells were positive for vimentin." (PMID 16584570, 2006). "Moreover, in tumor tissues from HCC patients treated with PPI, the density of VM structures (PAS+/CD31-) was markedly reduced, accompanied by the downregulation of VM-related markers (VE-cadherin, VEGFR1/2) and EMT markers (Twist1, Vimentin), as well as the upregulation of E-cadherin." (PMID 41019994, 2025). "Furthermore, we found that DOKD inhibited CT26+ tumor cell growth by regulating inflammation, metastasis, and angiogenesis by activating the IL-17/TLR4/NF-κB p65 pathway and inhibiting the activation of the Src/HIF-1α/Erk1/2/Snail/N-cadherin/Vimentin/MMP9 and Erk1/2/HIF-1α/STAT3/VEGFA pathways." (PMID 37239383, 2023). "In fact, most of the tumor cells do not survive within the circulation when they express the remaining cytokeratin filaments, while those expressing increased or de-novo α-actin and Vimentin may easily adapt to small vessels diameters." (PMID 36835963, 2023). "However, several IHC markers such as vimentin (92%), SMA (80%), muscle-specific actin (63%), S100 (7%), low Ki-67 expression, and lack of nuclear ß-catenin expression have been routinely used to confirm the origin of this tumor and to exclude other lesions mimicking DF." (PMID 37602060, 2023).
tumor (continued). "In this study, the expression of vimentin was significantly decreased and that of E‐cadherin was increased in PC‐11 and PC‐40 cells, indicating that knockout of PLD1 could attenuate EMT progression in CASKI cells, and this phenomenon was observed in mouse tumour tissues in vivo." (PMID 35775110, 2022). "In that study, we also identified a small number of mesenchymal-like (CK+| VIM+) cells, however with the exception of two cases, they were genomically normal and thus may represent cells from the tumor microenvironment (TME) rather than tumor cells that had been transformed through EMT." (PMID 35729213, 2022). "However, the spindle tumor component was diffusely strongly positive for vimentin and negative for AE1/AE3, whereas all the tumor cells were negative for neuroendocrine markers and other mesenchymal markers, such as desmin, SMA, myglobin, mygenin, S-100, DOG-1, CD34, CD117 and." (PMID 33761637, 2021). "In addition, as expected, Western blot demonstrated circPUM1 knockdown could repress N‐cadherin, vimentin, MAP3K2 protein expression and up‐regulate E‐cadherin protein expression, indicating that circPUM1 could promote the progress of EMT in HCC tumour." (PMID 33320435, 2021). "Furthermore, it has been reported that tumor-derived exosomes may carry different factors involved in the activation of EMT program including TGFβ, caveolin-1, HIF1α, vimentin and β-catenin thus improving the migration ability of cells inside a tumor and contributing to stromal remodelling." (PMID 36046089, 2021). "Through our immunohistochemical results, we could see that markers such as ACTA2, VIM, and MMP2 were mostly differentially expressed in the stromal area, including CAFs and vascular smooth muscle cells, but not in the tumor cells between the different risk score groups." (PMID 33747932, 2021). "HLA transgenic mice vaccinated with citrullinated vimentin and α-enolase peptides linked to an adjuvant (Modi-1 vaccine) can stimulate CD4+ T cells and generate potent anti-tumor responses resulting in tumor regression and eradication with no associated toxicity." (PMID 33859638, 2021). "Recruitment of Tregs, but not CD8+ T cells, may be affected by tumor vimentin expression." (PMID 32850341, 2020). "Furthermore, a main obstacle is to differentiate tumor cells undergoing EMT from stromal fibroblasts by IHC, and thus it is possible that we have underestimated the extent of stained tumor cells, especially considering a marker like vimentin which is present in fibroblasts." (PMID 32300922, 2020). "Moreover, CA III may increase the expression of the mesenchymal markers vimentin and several transcription factors of Slug and Twist through the FAK/Src signaling pathway to stimulate cell invasion and migration abilities similar to tumor metastasis." (PMID 32183030, 2020). "In addition to the survival advantage, PGP545 treatment also changed tumor cell phenotype, with the remaining tumor showing reduced levels of VEGF, vimentin, and collagen I. Histological analysis of these tumors showed high level of differentiation, suggesting that PGP545 may reverse tumor EMT." (PMID 33330449, 2020). "Thus, high levels of TCTP and vimentin might act as tumor enhancer for NSCLCs in both smokers and non-smokers." (PMID 32046740, 2020). "Similarly, ALDH3A1 is associated with the overexpression of NFkB and EMT markers such as VIM, FN1, and Zeb1, revealing that the enzyme, through a direct effect on the redox state of tumor cell metabolism, is involved in the process that links stemness, EMT, and inflammation in tumor cells." (PMID 31817719, 2019). "Moreover, GFP+ tumor cells harvested from the metastasized tibias and mammary fat pads of mice on day 28 had significantly greater sphere formation ability and expression of EMT genes, including N-cadherin, Twist, Snail1, and Vimentin, than those in circulation or injected into the mammary fat pads." (PMID 30651129, 2019).